HLA-DRA (major histocompatibility complex, class II, DR alpha)
Diseases named in the same sentence as HLA-DRA in open-access papers (continued):
Sharing a sentence is not in itself a finding about the gene and the disease.
tumor (continued). "Both HLA-DRA and HLA-DRB1 were underexpressed in NSCLC PBL T cells and overexpressed in NSCLC tumor C11 /C6-LAYN CD8 T cell clusters, C14 CD4/CD8 T-cell clusters, and suppressive tumor Tregs of CD4-C9-CTLA4 cells vs. other tumor-infiltrating Tregs of CD4-C8-FOXP3 cells." (PMID 35804895, 2022). "In addition, we observed that several MHC family members, such as HLA-DRA, HLA-DRB1, HLA-DPA1 and HLA-DPB1, were highly expressed in response tumour samples." (PMID 36581917, 2022). "Human MHC class II molecules (HLA-DMB, HLA-DMA, HLA-DRA, HLA-DOA) in the top 30 DMRs, which could attract inflammatory tumour-specific CD4+ T cells and dampen CD8+ T cell antitumour reactivity, were found to be hypomethylated in all CLL patients in our study." (PMID 36712882, 2022). "According to the Pearson’s correlation analysis, the tumor DLK2 level was negatively correlated with the expressions of M1 macrophage markers such as HLA class II histocompatibility antigen, DR α chain (HLA-DRA) (* p = 0.0278), CD11c (integrin α X, ITGAX) (p = 0.0557), and CD86 (p = 0.0783)." (PMID 35456435, 2022). "Notably, we found endothelial cells in stomach expressed major histocompatibility complex (MHC) class II genes such as HLA-DRA and HLA-DRB5, which was confirmed by multicolor immunohistochemistry (IHC) staining on tumor sections from GC patients." (PMID 35999201, 2022). "Next, we employed lineage-specific markers to annotate clusters into major cell types of the tumor, including T cells (CD3G, CD4, CD8A, CD28, and IL7R), B cells (CD19 and CD20), myeloid cells (HLA-DRA and CD14), fibroblasts (THY1 and ACTA2), and tumor cells (EPCAM and S100A)." (PMID 35634306, 2022). "We adjusted these results based on tumor purity, revealing strong and significant correlations between CD96 and CD8+ T cell markers (CD8A), general T cell markers (CD3D, CD3E, CD2), DC markers (HLA-DPB1, HLA-DRA, HLA-DPA1) in LGG." (PMID 33680972, 2021). "In addition, CD68 (macrophage) is highly correlated to antigen-presentation responses (HLA-DRA, r = 0.71 and 0.60 in normal and tumor tissues, respectively) and moderately correlated to GZMB (r = 0.54 and 0.47 in normal and tumor tissues, respectively)." (PMID 34758832, 2021). "From a transcriptomic perspective, tumour endothelial cells upregulate angiogenesis-related genes, such as CD99, KLF10, and ADAMTS4, while losing scar tissue-related Notch molecule HES4 and antigen presentation molecule HLA-DRA." (PMID 33532508, 2021). "However, a subset of genes up-regulated in microglia/tumor co-culture was found to be exclusively related to the concurrent presence of astrocytes (APOE, APOC2, HLA-DRA)." (PMID 31186414, 2019). "Another factor relating to better therapy response in HPV(+) tumors could be that HPV(−) exosomes are enriched in tumor-promoting and immunosuppressive proteins such as MUC-1, HLA-DRA, MUC-4, and MUC-16, which give protection to tumor cells against NK cell-mediated lysis." (PMID 41154440, 2025). "In contrast, the downregulation of HLA-DRA, HLA-A, HLA-B, and HLA-C, which are components of the MHC antigen presentation machinery, suggests a disruption in antigen presentation pathways, further hindering the immune system’s ability to recognize and eliminate tumor cells." (PMID 39860532, 2025). "It is worth noting that the interaction between HLA‐II molecules (such as HLA‐DRA, HLA‐DRB1, HLA‐DRB5, HLA‐DQB1, HLA‐DPB1, HLA‐DPA1, HLA‐DMB and HLA‐DMA) and the receptor CD4 was exclusively detected in the cell communication between malignant cells from single‐primary tumours and Tregs." (PMID 39601163, 2024).
tumor (continued). "In total, five populations were designated tumour clusters, which had various features: (TumourC0) CD74 and APOD; (TumourC1) IF16, JUN and HSPA1A; (TumourC2) S100B and SCRG1; (TumourC3) NEAT1 and MALAT1; and (TumourC4) WFDC2 and RNASE1 (HLA‐DRA, CD68, CD3D, CD3E)." (PMID 37784253, 2023). "Moreover, we observed a reduced expression of HLA class II molecules (CD74, HLA-DRA, HLA-DRB1, HLA-DMA), which might affect the number and function of CD4+ T lymphocytes in the tumor microenvironment." (PMID 36153593, 2022). "However, analysis of single‐cell RNA‐sequencing (RNA‐seq) of GB patient tumors revealed that tumor cells do not express CIITA nor genes encoding for MHC‐II antigen processing (CD74, HLA‐DMA, HLA‐DOA) and presentation (HLA‐DQA1, HLA‐DQB1, HLA‐DRA, HLA‐DRB1, HLA‐DRB5)." (PMID 39535369, 2025). "Based on the gene markers and the high expression of HLA-DPB1, S100A6, HLA-DRA, and other genes related to antigen presentation in GSVA, SC-C1 and SC-C3 cells were mainly enriched in hematopoiesis, suggesting that SC-C3 cells may be related to tumor vascular proliferation." (PMID 36304995, 2022). "Moreover, we observed that immune‐related and cell adhesion‐related genes such as CD83, HLA‐DRA, JAK3, CEACAM6, and ITGB238, 39, 40, 41 exhibited high H3K27me3 modification in tumour cells, suggesting that their expression may be suppressed by H3K27me3 to facilitate immune escape of tumour cells." (PMID 39210544, 2024). "AR was expressed in a median of 32.9% of CD163 and/or HLA-DRA and/or CD14 expressing cells in the Tumour area, which was not significantly different from cells in the tumour border or in the distant area (median 34.2% and 35.2%, respectively)." (PMID 32908142, 2020). "Other proteins, including HLA-A, HLA-DMA, HLA-DQA1, HLA-DQB1, HLA-DRA, HLA-DRB1, and HLA-DRB5, were not reported on tumor–host immunological interactions, which indicated the proteins need further studies to testify them as novel OC biomarkers for tumor immunology." (PMID 31258820, 2019).
cancer (61 papers, 2007 to 2026). A tumor composed of atypical neoplastic, often pleomorphic cells that invade other tissues. "The GSEA results showed that a high expression of HLA-DRA is mainly associated with cancer-associated cellular immunity whereas low expression is mainly associated with substance metabolism." (PMID 35585639, 2022). "Based on previous studies, Fibro_FAP was classified as inflammatory cancer-associated fibroblast (iCAF)-like, Fibro_ACTA2 as myofibroblastic cancer-associated fibroblast (myCAF)-like, and Fibro_HLA-DRA and Fibro_AGR2 as antigen-presenting cancer-associated fibroblast (apCAF)-like." (PMID 39722065, 2025). "A proportion of EPCAM+ cancer cells (median, 21,286; range, 129–197,205) expressed HLA-DRA, with a median ratio of 10.28% (range, 1.08–79.6%)." (PMID 40925909, 2025). "Consistently, overexpression of HLA-DRA increased the proliferative capacity of T24 and 5637 cancer cells, as confirmed by CCK-8 and colony formation assays." (PMID 41281745, 2025). "For instance, boundary cluster 1_2, which comprises immune infiltrates as well as both in situ and invasive cancer, is characterized by the immune gene HLA‐DRA." (PMID 40245302, 2025). "The c04_CXCL12 subgroup displayed characteristics of both antigen‐presenting cancer‐associated fibroblasts (apCAFs), marked by CD74 and HLA‐DRA, and immune‐related cancer‐associated fibroblasts (iCAFs), indicated by CXCL14 and CXCL12." (PMID 39716897, 2024). "In conclusion, we have validated the predictive value of HLA-DRA in determining the responsiveness of cancer patients to ICI therapy." (PMID 38931345, 2024). "Additionally, HLA-DRA may represent as a predictive marker for cancer risk and prognosis." (PMID 37715206, 2023). "By incorporating the weak genes CSNK2B, HLA-A, HLA-C, and HLA-DRA, the PD-1, PD-L1 cancer immunotherapy pathway was significantly enriched." (PMID 37065470, 2023). "HLA-DRA was also positively correlated with the expression levels of immune checkpoints in pan-cancer." (PMID 35794593, 2022). "Human leukocyte antigen DR alpha chain (HLA-DRA) has been reported to be involved in the progression of a variety of cancers." (PMID 35185791, 2022). "The GSEA results showed that a high expression of HLA-DRA is mainly enriched in cancer-related cellular immunity whereas low expression is mainly enriched in substance metabolism." (PMID 35585639, 2022). "The NPS was significantly and positively associated with HLA genes, including TAP1, HLA-E, HLA-DRA, B2M, TAP2, HLA-DPA1, and HLA-DOA in all cancers." (PMID 36170029, 2022). "Except for several cancer types, HLA-DRA was positively correlated with the expression levels of these immunomodulators." (PMID 35794593, 2022). "HLA-DRA is a potential biomarker that can be used to evaluate the antigen-presenting efficacy for cancer monitoring or immune therapy effectiveness evaluation." (PMID 34575089, 2021). "Accordingly, we observed increased expression of IFNG-related genes in the CD8HIGH HPV+ subset, e.g., CCL5, CXCL9/13, CXCR6, and HLA-DRA, which contribute to a pan-cancer signature suggested to predict an optimum response to anti-PD1 immune checkpoint-therapy." (PMID 34771506, 2021). "Especially in septic patients but also in the context of cancer, low HLA-DRA levels have been reported." (PMID 31155685, 2019). "Moreover, in neutrophils, the HLA-DRA-JUN-FOS was shown to play a key role in the progression of monoclonal gammopathies of uncertain significance (MGUS) to active MM by supporting cancer hallmarks and MM pathophysiology." (PMID 42278510, 2026). "Overexpression of HLA-DRA in vitro enhanced cancer cell proliferation and migration." (PMID 41281745, 2025). "The main pathways of methylome biomarkers were associated with calcium signalling (CACNA1E, RYR2, RYR3), cancer pathways (DCC, RASSF1, WNT1, CTNNA2), multiple neurodegenerative diseases (WNT1, DNAI1, RYR2, RYR3), immune system disorders and cell adhesion (HLA-DRA, HLA-DRB1, HLA-DRB5)." (PMID 40524349, 2025).
cancer (continued). "HLA-DRA is a subunit of HLA-DR, which plays a critical role in human cancers." (PMID 35794593, 2022). "Furthermore, HLA-DRA was related to the features of inflamed TME in not only NSCLC but also in most cancer types." (PMID 35794593, 2022). "Moreover, pan-cancer investigation and validation revealed that HLA-DRA was a pan-cancer classifier for immuno-hot tumors." (PMID 35794593, 2022). "HLA class II molecules like HLA-DPB1, HLA-DRA, HLA-DRB1, and HLA-DQB1 are associated with antigen processing and presentation to CD4+ T cells, and the down-regulation of these genes is related to poor prognosis of cancers." (PMID 36417424, 2022). "In kidney renal clear cell carcinoma, HLA-DRA serves as a reliable biomarker and may play a vital role in cancer immunotherapy." (PMID 34136377, 2021). "However, the immunological role of HLA-DRA in other cancer types was unclear." (PMID 35794593, 2022). "Furthermore, the pan-cancer analysis revealed that HLA-DRA identifies high immunogenicity." (PMID 35794593, 2022). "To quantify this finding, we developed an HLA‐DR score based on all upregulated HLA‐DR genes (HLA‐DRA, HLA‐DRB1, and HLA‐DRB5) and found that HBV cancer cells exhibited significantly higher HLA‐DR scores than NBNC cancer cells." (PMID 40464412, 2025). "Differential gene expression and gene ranking analyses revealed that the expression of CD74, HLA-DRA, HLA-DRB1, and FXYD3 was elevated in MHC-II+ cancer cells, whereas the expression of LOXL2 and DLL4 was increased in MHC-II− cancer cells." (PMID 41281745, 2025). "Volcano plot analysis highlighted that HLA‐DRA and HLA‐DRB1 were significantly upregulated in high HLA‐DR cancer cells, particularly in HBV samples." (PMID 40464412, 2025). "In most of the cancers, there was a significant correlation between UBE2C gene expression and HLA‐DMB, HLA‐DOA, HLA‐DPA1, HLA‐PDB1, HLA‐DRA, and HLA‐E." (PMID 38577722, 2024). "We noticed that some MHC class II genes (HLA-DMA, HLA-DPA1, HLA-DPB1, HLA-DRA, HLA-DRB1) were significantly down-regulated in cancer cells with relatively poor differentiation states compared with those with better differentiation states for 5/6 mGC patients." (PMID 37347037, 2023). "Genes in response to interferon gamma, including CCL20, CCL25 and CD74, and antigen presentation-related genes, such as HLA-DPA1, HLA-DRA and HLA-DRB, were significantly upregulated in the cancer cells of immune-rich type tumors." (PMID 36729271, 2023). "In specific, TIS is referred to as an 18‐gene signature (CCL5, GZMK, CD3D, CD3E, CD2, HLA‐DRA, IL2RG, NKG7, CIITA, CXCR6, LAG3, TAGAP, HLA‐E, CXCL13, IDO1, CXCL10, STAT1, and GZMB), which was related to the response to ICIs in various cancers." (PMID 37434432, 2023). "Among them, HLA-DMB, HLA-DRA, IL12A, and IL12B, whose determinant role in cancer outcome as immune adjuvants has already been published, are found in the top 500 TG2 positively correlating genes." (PMID 35725560, 2022). "As for MHC molecules, we found the MHC class II molecules including HLA-DPA1, HLA-DPB1, HLA-DRA, HLA-DRB1, HLA-DQA1, HLA-DQB1 showed a stronger relation with PD-1 than other MHC molecules in some cancer types." (PMID 30607140, 2018). "Gene Ontology (GO) and Kyoto Encyclopedia of Genes and Genomes (KEGG) analyses revealed that the top upregulated genes (start vs. end) in cancer‐pre cells (Curve1 and Curve2) were enriched in antigen processing and presentation pathways, such as CD74, HLA‐DRB1, HLA‐DRA, PSME1/2, and CTSB." (PMID 40860436, 2025). "Notably, HLA-A, HLA-DPA1, HLA-DQB1, HLA-DRA, HLA-DRB1, HLA-DRB5, and HLA-J consistently negatively correlated with the PLK1 expression in the 12 cancer types." (PMID 30631355, 2018). "Moreover, upregulation of CXCL13 and CXCL14 are associated with a reduction in HLA-DRA and MHC-Class II, because of which cancer-specific antigens are not presented by dendritic cells and hence cancer cells evade immunosurveillance." (PMID 32752229, 2020).
cancer (continued). "We find that the genes specifically expressed in the supratentorial tumors from these publications (such as HLA-DRA, LYZ, CD74, F13A1, and TRIM22) tend to be expressed in cells within the microglia-type cluster, whereas the infratentorial tumors have higher expression of cancer cell-related genes." (PMID 31427603, 2019). "Additionally, several studies reported that HLA-DRA could affect tumors and NR4A1 has been correlated with various carcinomas." (PMID 26367387, 2015).
infection (7 papers, 2017 to 2024). The state of being infected such as from the introduction of a foreign agent such as serum, vaccine, antigenic substance or organism. "Immune-suppressive phenotypes were also detected in cDCs during infection, with notable downregulation of HLA-DR genes HLA-DRA and HLA-DRB1 along with multiple paralogues (HLA-DPA1/B1 and HLA-DQA1/B1) in cDCs but not cytokine/chemokine genes." (PMID 37968278, 2023). "Future longitudinal studies that characterise the early transcriptomic events should provide more information on the kinetics of MCEMP1 and HLA-DRA gene and protein expression over the entire course of infection." (PMID 36801619, 2023). "Humoral immune response related GO terms such as humoral immune response was common to both, while B cell mediated immunity (C1QB, HLA-DRA, C1QC, FCERIG, CIQA, CLU) was uniquely in subclinical infection." (PMID 32012176, 2020).
neurodegenerative disease (4 papers, 2016 to 2025). A disorder of the central nervous system characterized by gradual and progressive loss of neural tissue and neurologic function. "This process was accompanied by increased expression of CLU, a gene involved in cell death and neurodegenerative diseases, and decreased expression of the immune genes HLA-DRA, HLADRB1 and CD74." (PMID 37275903, 2023).
immune diseases (2 papers, 2023 to 2025). "HLA-DRA genes play an essential role in immune diseases such as RA and SLE and may be involved in the pathogenesis of immune system diseases in the TK population." (PMID 37308851, 2023).
gastrointestinal tumor (1 paper, 2024). "We further found NOTCH3 levels in gastrointestinal tumor to correlate with markers of Dendritic cell(HLA-DPB1, HLA-DRA, HLA-DPA1, BDCA-4), Tfh(T-bet, STAT4, STAT1, TNF-α), Treg cells (FOXP3, CCR8, STAT5B, TGFβ) and T cell exhaustion (PD-1, CTLA4, LAG3, TIM-3)." (PMID 38906903, 2024).
inflammation (1 paper, 2021). Aberrant reaction of the microcirculation characterized by movement of fluid and leukocytes from the blood into extravascular tissues. "That inflammation, immune system activation and imbalance, and cell proliferation and adhesion migration were mainly affected by HLA-DRA, SYK, CTLA4, VAV1, NRAS, and JAK3 signaling pathways was suggested to be the potential molecular mechanism for pulmonary inflammation and fibrosis in ACO." (PMID 33869177, 2021).
kidney disease (1 paper, 2021). "Our findings indicate that a high expression of different co-DEGs was correlated with a low glomerular filtration rate in kidney disease samples (IL10RA, HLA-DPA1, r = −0.490, p < 0.001; IRF8, HLA-DRA, r = −0.500, p < 0.001; HLA-DPB1, r = −0.510, p < 0.001; HLA-DMA, r = −0.480, p < 0.001)." (PMID 34692653, 2021).
mitochondrial disease (1 paper, 2022). "Other genes with contributing missense variants in JIP were PARS2, associated with mitochondrial disease, and HLA-DRA, which plays a key role in the human immune system." (PMID 35864541, 2022).
HLA-DRA also shares sentences with these, for which no sentence is quoted: hepatocellular carcinoma (6 papers); adenocarcinoma (2); autoimmune thyroid disease (2); celiac disease (2); chronic pancreatitis (2); Clear Cell Renal Cell Carcinoma (2); Graves disease (2); head and neck squamous cell carcinoma (2); hypothyroidism (2); influenza (2); lung squamous cell carcinoma (2); nasal polyp (2); neurological diseases (2); schizophrenia (2); acute myeloid leukemia (1); adenoma (1); adrenocortical tumors (1); alopecia areata (1); angina pectoris (1); Arthritis (1); atrial fibrillation (1); bacterial infection (1); basal cell carcinoma (1); brain disorder (1); breast invasive carcinoma (1); breast tumors (1); carditis (1); cervical adenocarcinoma (1); cervical intraepithelial neoplasia (1); cervical tumor (1).
A further 45 diseases each share a sentence with HLA-DRA in 1 paper.